NOTCH2 (notch receptor 2)
Diseases named in the same sentence as NOTCH2 in open-access papers (continued):
Sharing a sentence is not in itself a finding about the gene and the disease.
tumor (continued). "For instance, the fully human IgG2 antibody Tarextumab (TRXT, OMP59R5) combined with chemotherapy has been shown to significantly reduce tumor recurrence in patient-derived SCLC xenografts, by targeting Notch2/Notch3." (PMID 27847554, 2016). "Mechanistically, we uncover an innovative mechanism of the regulation of Notch2 via the JAK/STAT3 signaling pathway and subsequently-induced tumor malignancy in response to the radiation." (PMID 27462787, 2016). "A recent study showed that NOTCH2 and its ligand Jag1 are highly expressed in human HCC tumours, suggesting activation of NOTCH2 signalling in HCC45." (PMID 25985737, 2015). "First, we analysed NOTCH2 activation levels in HCC tumour tissues and peri-tumour tissues derived from Park's cohort (GSE36376)." (PMID 25985737, 2015). "Different and partly opposite roles in one tumor entity have been found for NOTCH1 and NOTCH2, indicating specific functions of the two receptors." (PMID 25954607, 2015). "RT-qPCR analysis for NOTCH1, NOTCH2, HEY1 and HES1 was conducted on the normal bone/matched OSA and DFI tumor sample sets." (PMID 23816051, 2013). "By in silico analysis, miR-34a is predicted to target several members/genes of notch signaling: Notch1, Notch2 and Jagged1, which were reported to play critical roles in EMT of tumor and endothelial cells." (PMID 22363487, 2012). "A significant post-therapeutic increase in NOTCH2, LGR5 and POU5F1 expression was found in tumours with different tumour regression grades." (PMID 22970250, 2012). "Analysing these residual tumour cells we identified a gene expression pattern encompassing GSK3B, CTNNB1 and NOTCH2, which strongly predicts prognosis of the patients." (PMID 22970250, 2012). "IL-1β/TGF-β-induced neurospheres display up-regulated expression of stemness factor genes (nestin, Bmi-1, Notch-2 and LIF), and increased invasiveness, drug resistance and tumor growth in vivo: hallmarks of GSCs." (PMID 22330721, 2012). "CD133-positive cells, isolated from the tumor, expressed stem cell markers including nestin, CD133, Ki67, Sox2, EFNB1, EFNB2, EFNB3, Cav-1, Musashi, Nucleostemin, Notch 2, Notch 4, and Pax6." (PMID 22995409, 2012). "Conversely, expression of an active form of Notch2 increased tumor growth and in vivo delivery of GSI consistently blocked tumor growth, and significantly prolonged survival." (PMID 21078177, 2010). "Additionally, N1ICD overexpression upregulated the EMT marker VIM to a greater extent than N2ICD overexpression, suggesting distinct roles for NOTCH1 and NOTCH2 in regulating EMT and tumor-intrinsic STING expression." (PMID 40627448, 2025). "Herein, we selected two representative Notch receptors (NOTCH1 and NOTCH2), NICD (NOTCH1 intracellular domain, also known as activated NOTCH1), and HES1 (downstream effector) as targets and conducted an immunohistochemical study on tumor samples." (PMID 40387567, 2025). "We identified newly emerging mutations in genes that were not covered by our targeted NGS panel such as ATM, NOTCH2, EP300, ARID1A and MAP3K1 and also noticed an increase in tumor mutational burden (TMB) in some cases during progression." (PMID 40973765, 2025). "This has led to the consideration that the expression of Jagged-1, in the absence of the simultaneous expression of Notch-2, has little predictive significance on tumor evolution." (PMID 40429321, 2025). "NOTCH2, NOTCH3, and NOTCH4 may act as oncogenes in cSCC, with studies showing high expression of NOTCH2 and NOTCH3 in cSCC tumor tissues." (PMID 39925808, 2025). "Specifically, NOTCH1 may be tumor-suppressive and inhibit the epithelial-to-mesenchymal transition (EMT), while NOTCH2 may be tumor-promoting for the EMT procedure." (PMID 40277814, 2025). "The int-CAs showed higher expression of IR transcripts of NOTCH1 and NOTCH3 compared to the other tumor types but did not have the IR transcripts of NOTCH2 and NOTCH4 (p < 0.05)." (PMID 39101773, 2024).
tumor (continued). "Our data, however, suggest that the absence of Notch1 or Notch2 tends to accelerate tumor development in BP mice." (PMID 36672468, 2023). "NOTCH2 expression was strongly linked to HES1 expression, while other NOTCH gene levels were not, as indicated by RNA-sequencing analysis of desmoid tumor samples." (PMID 37728427, 2023). "Notch wild-type tumours were scattered throughout the data set, and there was no obvious clustering of the Notch2 knockout tumours." (PMID 37686600, 2023). "Additionally, the study revealed that neurogenic locus notch homolog protein 2 (Notch2) is possibly a direct target of miR-204 and proposed the BANCR/miR-204/Notch2 axis as a mediator of cell proliferation and tumor progression." (PMID 37629553, 2023). "Among Notch receptors, NOTCH-2 expression showed no significant change among different tumor grades and stages." (PMID 36476410, 2022). "It would be interesting to determine whether Notch3, which represses the proliferation of adult NSCs, contributes to the tumor suppressor activity of RBP-Jk in cooperation with Notch1 and Notch2." (PMID 36358826, 2022). "The data from our previous study demonstrated that overexpression of Notch2 could inhibit EMT in NPC cells in vitro and in vivo and that inhibition of EMT could enhance the radiosensitivity of tumor cells." (PMID 34224316, 2021). "Unlike Notch1, Notch2 has a more substantial role in tumor growth and plays a suppressive role in tumor angiogenesis through PTEN induction and AKT dephosphorylation." (PMID 36643842, 2021). "Overexpression of Notch2 and Jagged1 has been shown in gemcitabine resistant pancreatic cancer cells, whereas Notch1 is a crucial downstream mediator of Kirsten rat sarcoma viral oncogene homology (KRAS), and control tumor sphere formation of pancreatic cells." (PMID 33670230, 2021). "Tspan5 correlation analyses of TCGA tumour samples revealed that Tspan5 expression is positively correlated with the expression of ADAM10, Notch1, Notch2, Notch3, Notch4, Hey1, vimentin, N‐cadherin and Snail, whereas it is negatively correlated with E‐cadherin in HCC tissues." (PMID 33955149, 2021). "Notch1 and Notch2 were found to be downregulated in tumor infiltrating T cells but not in splenic T cells of tumor-bearing mice." (PMID 32922403, 2020). "Furthermore, the aggressive TNBC cell line HCC1187, which harbours a chromosomal translocation in the Notch 2 gene, rendering it resistant to GSIs, demonstrated sensitivity to CB-103, suggesting that it may be a more suitable treatment strategy for Notch-addicted tumours with such genotypes." (PMID 32575680, 2020). "Enhanced tumor growth was observed in the CAM assay after Notch2 ICD, but not Notch1 ICD, expression." (PMID 29993038, 2018). "Furthermore, we checked the protein levels of NOTCH2, YEATS4, HEY1, and HES6 in tumor tissues of the xenograft experiment." (PMID 29706630, 2018). "Similarly, treatment of tumor bearing mice with an agonistic NOTCH2 antibody enhanced CD8 T-cell cytotoxicity and reduced tumor size." (PMID 30967879, 2018). "We found that miR-1 can down-regulate Notch2 protein in tumor cells, but no change in Notch2 mRNA was observed." (PMID 29581534, 2018). "We observed Notch2 immunoreactivity in the cytoplasm and nucleus of tumor cells, with no Notch2 expression being detected in mesenchymal cells." (PMID 29545603, 2018). "In contrast, nuclear positivity for Notch2 in the tumor tissues was markedly stronger than that seen in the non-neoplastic brain tissue." (PMID 29258209, 2017).
tumor (continued). "Compared with nontumor normal tissues, downregulation of Notch1 and Notch4 was observed in HCC tissues, while Notch2 expression was not significantly different between tumor and normal tissues." (PMID 28568708, 2017). "In the tumor network, PVT1 competing for cancer related genes such as BRCA1, NOTCH2 and CDK1/4." (PMID 27580177, 2016). "This suggests that either Notch2 or Notch3 inhibition can have therapeutic activity in SCLC cells or that non-cell autonomous effects on tumor stroma mediated by Notch2/3 inhibition are responsible for this effect." (PMID 27148486, 2016). "This study found Notch1, Notch2, and Notch4 to be involved in stromal-dependent CLL resistance to fludarabine and cyclophosphamide chemotherapy, with mesenchymal stem cells dramatically increasing tumor cell survival." (PMID 26934331, 2016). "Consequently, C8orf4-overexpressing tumours showed much less N2ICD nuclear translocation and reduced expression levels of NOTCH2 target genes compared with control tumours." (PMID 25985737, 2015). "All genes showed expression mostly in vivo and not in vitro, except Notch 2, suggesting that the tumor microenvironment favors expression and/or full activation of the Notch signaling pathway and other signaling pathways." (PMID 26059540, 2015). "We identified mutations that seem to be heterozygous and clonal as they show allele frequencies of >40 % in the WES and 46–53 % in the validation experiments (NOTCH2, SMYD1, MYD88), with the proximity to 50 % providing an indirect evidence for high tumor cell purity." (PMID 26498442, 2015). "Further, in the tumor-draining LN (TDLN), tumor-specific Vβ8.1/2+ CD8+ T cells representing a frequency of 8-10% (data not shown) showed increased expression of the surface receptor and mRNA of Notch1 and Notch2 following bortezomib treatment." (PMID 26431276, 2015). "On day 50 after inoculation, tumor weight in the Notch2-shRNA group was significantly lower than that in the nontransfection and negative-shRNA groups (0.55±0.1 vs. 1.57±0.29 and 1.23±0.52g, respectively; P<0.01)." (PMID 25323114, 2014). "The tumor growth curve showed that tumor volume was significantly lower in the Notch2-shRNA group than that in the nontransfection and negative-shRNA groups 40 days after inoculation (P<0.05)." (PMID 25323114, 2014). "The results of the differential expression analysis indicate a prominent role for NOTCH2 and chemotherapy resistance in GC, which seems to be related to an effect of the drugs on NOTCH2 expression rather than to an enrichment of NOTCH2 expressing tumour cells." (PMID 22970250, 2012). "The comparison of GSK3B and CTNNB1 expression levels between pre- and post-therapeutic tumour samples revealed no clear differences, whereas a significant increase in the expression of NOTCH2 was found." (PMID 22970250, 2012). "They further indicate a prominent role for NOTCH2 and chemotherapy resistance in GC, which is more likely related to an effect of the chemotherapeutic agents on NOTCH2 expression rather than to an enrichment of NOTCH2 expressing tumour cells." (PMID 22970250, 2012). "Taken together, our findings confer that Notch1, but not Notch2 is a tumor suppressor and plays a crucial role in proper skin development and differentiation." (PMID 21042537, 2010). "Nonspecific NOTCH inhibitors may disrupt NOTCH2, which functions as a tumor suppressor in CRC,42–44 potentially promoting tumorigenesis." (PMID 41423446, 2025). "Similarly, CLL xenotransplant models treated with bepridil significantly reduced tumor infiltration with no remarkable toxicity nor activity on NOTCH2 WT protein." (PMID 38255842, 2024). "Targeting NOTCH2 could potentially reduce GSC survival and tumor growth." (PMID 39063221, 2024). "Moreover, Notch 1 and Notch 2 appear to have opposite functions in embryonic brain tumors and pancreatic ductal adenocarcinoma (PADC), adding another layer of complexity on the role of Notch signaling in tumor progression." (PMID 37255594, 2023).
tumor (continued). "In the present study, we demonstrate that Kir2.1, an inwardly-rectifying potassium channel, is highly expressed in non-WNT/SHH MBs, which promotes tumor cell invasion and metastasis by recruiting Adam10 to enhance S2 cleavage of Notch2 thereby activating the Notch2 signaling pathway." (PMID 35273141, 2022). "Although no specific tumour-related gene was shared among the three groups, NOTCH2 was shared between BTG and PTCb while AR, HSP90AB1 and GNAS were shared between BTG and PTCa suggesting their possible roles in the BTG-to-PTCb and BTG-to-PTCa transformation, respectively." (PMID 36686473, 2022). "In this study, we report that Kir2.1 is preferentially expressed by non-WNT/SHH MBs and contributes to tumor progression by recruiting disintegrin and metalloproteinase domain-containing protein 10 (Adam10) to enhance S2 cleavage of Notch2, thereby activating the Notch2 pathway." (PMID 35273141, 2022). "Another study showed that negative Notch2 regulation induced by siRNA in gastric cancer cells increases the invasive function of tumor cells, enhances the expression and activity of MMP9, and increases the phosphorylation of the PI3K pathway, as with growing p-Akt was shown." (PMID 36643842, 2021). "Regardless of whether Notch signaling promotes T cells into effector cells or memory cells, Notch2 but not Notch1 signaling has been demonstrated to be essential for potent anti-tumor immunity." (PMID 33585446, 2020). "Mice injected with NOTCH2KO CNE-2 cells developed significantly more metastatic foci in the liver than mice injected with Ctrl CNE-2 cells with no altered primary tumor growth in the spleen (P < 0.05), indicating that NOTCH2 suppression promotes NPC cell metastasis in vivo." (PMID 31699119, 2019). "Mice injected with oeNOTCH2 5-8F cells developed significantly fewer metastatic foci in the liver than mice injected with oeVec 5-8F cells with no alteration of primary tumor growth in the spleen (P < 0.05), indicating that NOTCH2 overexpression inhibits NPC cell metastasis in vivo." (PMID 31699119, 2019). "The miR-1 in tumor tissue was correlated with Notch2 protein level, but not with Notch2 mRNA." (PMID 29581534, 2018). "In contrast, NTN1 and Notch2 did not co-localize in same tumor cells." (PMID 28069038, 2017). "Interestingly, the only Lck-Dlx5 tumor (1/11) without overexpression of Notch1 and Notch3 instead showed upregulation of Notch2, further suggesting an essential role for aberrant Notch signaling in Dlx5-driven T-cell lymphomagenesis." (PMID 28122332, 2017). "However, the changing expression of KLF2 and NOTCH2 during tumor progression has not been delineated." (PMID 28887496, 2017). "Results from our ChIP-Seq analysis identified oncogenic c-Myc, Cyclin D1, Ets2, Akt1 and Notch2, pro-inflammatory Hsp90, pro-lymphangiogenic VEGF-C, and pro-apoptotic p27 as novel transcriptional targets of MTA1, revealing its ability to simultaneously activate multiple tumor-promoting pathways." (PMID 26943043, 2016). "Furthermore, siRNA-mediated knock-down of Notch1 or Notch2 impaired tumor formation in xenografts but unfortunately, GSIs were not tested in this setting." (PMID 25601901, 2014). "They found low levels of Notch3 staining in normal prostate sections and decreased Notch2 expression with increasing tumor grade but did not report whether they detected Notch2 in normal prostate tissue." (PMID 24199173, 2013). "An important finding from our in vivo study is that although neither Notch1 nor Notch2 acts as a tumor suppressor to fully substitute Pten in BRFAV600E induced melanomagenesis, the loss/decrease of Notch proteins appeared to accelerate tumor formation and promote tumor growth." (PMID 36672468, 2023).
tumor (continued). "Further, in patients-derived cells, silencing of Notch 1 or Notch 2 does not counter resistance to β-catenin inhibition, rather pharmacological pan-Notch inhibition is needed to overcome resistance and its effect on in vitro tumor sphere formations as well as in vivo liver metastases." (PMID 34179007, 2021). "To follow up on these findings, suggesting that Notch1, and possibly also Notch2 may be connected to the cytokine-stimulated integrative system that we study in TNBC, we next used the TCGA dataset to analyze the relevance of Notch1 and Notch2 to the tumor-stroma-inflammation network." (PMID 31105691, 2019). "Our study reports a previously unrecognized epidermal expression of PDX1 and adds further evidence for a pivotal role of Notch1 but not Notch2 as a tumor suppressor in the skin, which may be particularly interesting in the light of new therapeutic approaches targeting single Notch receptors." (PMID 21042537, 2010). "Later, Maraver and colleagues confirmed the tumour suppressive role of NOTCH1, but they observed another role for NOTCH2, whereas NOTCH3 was not studied." (PMID 41008920, 2025). "SMARCA4 expression was positively correlated with multiple NE genes including SYP, CHGA, INSM1, DLL3 and NCAM1 and negatively correlated with non-NE factors REST, NOTCH2, and YAP1 in both SCLC cell lines and patient tumor databases." (PMID 39080761, 2024). "It was found that the administration of anti-Notch2 antibodies suppressed the development of HCC/CCC, while the administration of anti-Notch3 antibodies exhibited no such effects on tumor progression." (PMID 35064244, 2022). "In summary, we show that the nuclear NOTCH2 inhibitor gliotoxin has global effects on the NOTCH signaling network in CLL cells, including the recovery of a newly identified non-canonical tumor suppressing NOTCH3 activity." (PMID 32570839, 2020). "Cell-specific analyses complemented these results by indicating that NOTCH1, NOTCH2 and NOTCH3 were up-regulated by TNFα in the tumor cells but not in the MSCs." (PMID 31105691, 2019). "Interestingly, the expressions of NOTCH1, NOTCH2 or NOTCH3 are highly correlated with those of many prognostic immune receptors, implying that Notch signaling might be important in the regulation of tumor immune response or tumor microenvironment, which, in fact, has been reported in many studies." (PMID 31185958, 2019). "We found that the expression levels of NOTCH2, HEY1, and HES6 were lower in lncAKHE-silenced HCC cell-derived tumor tissues than in control tumor tissues, whereas YEATS4 expression was not affected." (PMID 29706630, 2018). "NOTCH2 and HEY1 mRNA expression was also elevated in tumors relative to normal bone, but was not differentially expressed between the DFI tumor groups." (PMID 23816051, 2013). "In summary, these data show that gliotoxin recovers a non-canonical tumor-suppressing NOTCH3 activity, indicating that nuclear NOTCH2 inhibitors might be beneficial compared to pan-NOTCH inhibitors in the treatment of CLL." (PMID 32570839, 2020). "This is illustrated for example by studies on tumor initiation (Notch1; Notch3), stem cell control (Notch1; Notch4; Jag1; Jag2; DLL1), angiogenesis (Notch1; DLL4) invasion and metastasis in remote organs (Notch1; Notch2; Jag1; DLL1)." (PMID 32605277, 2020). "Noticeably, this latter work also disclosed that unlike Notch1 or Notch3, which displayed increased levels, Notch2 was decreased in advanced tumors in the KrasG12D NSCLC model, where it furthermore displayed a tumor suppressor function through modulation of the Wnt/β-catenin pathway." (PMID 32784481, 2020). "Furthermore, we found that Notch2 is the major driver of the biliary phenotype in AKT/Yap tumors, whereas inactivation of Notch1 slightly delays tumor development without affecting the histological features of AKT/Yap ICC lesions." (PMID 29545603, 2018).
tumor (continued). "Besides, the correlation between the miR-181c overexpression after -and possibly induced by- the MAP treatment and the absence of the tumor relapse, can be partially explained considering that among its putative targets figure genes regulating the cell cycle, like GATA6, MAP2K1, PPM1A and Notch2." (PMID 26062442, 2015).